Y_RNA (Y RNA )
Gene: Miscellaneous RNA gene on chromosome 2 (128,350,829 to 128,350,927, reverse strand). Ensembl gene ENSG00000252742.
Homologues: Orthologues: chimpanzee Y_RNA (100% identical), pig Y_RNA (68% identical). Paralogues in human: Y_RNA (79% identical), Y_RNA (78% identical), RNY1P5 (77% identical), Y_RNA (77% identical), Y_RNA (76% identical), Y_RNA (75% identical), RNY1P1 (74% identical), Y_RNA (74% identical), RNY1P14 (73% identical), RNY1P6 (73% identical), Y_RNA (73% identical), RNY1P11 (72% identical), and 92 more.